EFEMP1 (EGF-like fibulin extracellular matrix protein 1)
Diseases named in the same sentence as EFEMP1 in open-access papers (continued):
Sharing a sentence is not in itself a finding about the gene and the disease.
breast carcinoma (29 papers, 2009 to 2025). "In breast cancer, miR-9-mediated down-regulation of EFEMP1 has been implicated in the transformation of normal fibroblasts into cancer-associated fibroblasts." (PMID 39822989, 2025). "Aiming at investigating EFEMP1 role in the conversion of normal to cancer-associated fibroblasts in the breast cancer microenvironment, we analyzed its expression level in six matched paired NFs/CAFs obtained from breast malignances (two grade III, three grade II and one grade I; GSE20086)." (PMID 32972039, 2020). "Although contradictory data suggesting EFEMP1 to be a bad prognostic indicator have been also published, our data support the beneficial role of EFEMP1 in breast cancer." (PMID 38217262, 2024). "In breast cancer, EFEMP1 was found downmodulated in sporadic malignancies but there is also evidence of pro-tumor activities." (PMID 32972039, 2020). "As is the case with several other tumor-promoting genes, we found in examining human breast cancer datasets using Oncomine that the fibulin-3 gene EFEMP1 is often amplified in TNBC patients." (PMID 30046386, 2018). "After specifically filtering for breast cancer datasets showing a frequency of tumor reoccurrence, we observed significant correlations between EFEMP1 upregulation and a higher incidence of breast cancer reoccurrence." (PMID 27270657, 2016). "We also investigated the roles of EFEMP1 in the invasion and migration of human breast cancer cells using a transwell migration assay." (PMID 27270657, 2016). "Decrease or loss of EGF‐containing fibulin‐like extracellular matrix protein 1 (EFEMP1) has been shown in human breast cancer." (PMID 24963031, 2014). "In breast cancer, EFEMP1 is a new candidate tumor suppressor gene." (PMID 34204134, 2021). "Interestingly, in a dataset comparing gene expression of CAF from breast cancer patients resistant vs sensitive to neoadjuvant chemotherapy, EFEMP1 was found significantly downmodulated in the resistant group." (PMID 32972039, 2020). "However, since only EFEMP1 downmodulation was validated in public datasets comparing tumor vs normal stroma of breast cancer patients, we decided to focus our efforts on studying EFEMP1 contribution to the observed phenotype." (PMID 32972039, 2020). "Although EFEMP1 seems to be important in the development of breast cancer, its role in BCSC functions remains unknown." (PMID 27270657, 2016). "Therefore, to further confirm the connection between EFEMP1 and breast cancer tumorigenesis in vitro, we assessed the effects of EFEMP1 knockdown on tumorigenesis using an in vivo Hs578T cell model." (PMID 27270657, 2016). "Moreover, to investigate the oncogenic potential of hypoxia and its regulatory role in HIF2α-induced EFEMP1 expression in breast cancer, we analyzed the EFEMP1 expression levels in the presence or absence of HIF2α inhibitor 76 under CoCl2 treatment." (PMID 27270657, 2016). "Moreover, since breast cancer is a complex and highly heterogeneous disease, to gain a better understanding of these complexities we analyzed EFEMP1 expression in public profiles of human dermal fibroblasts conditioned with three breast cancer cell line models (GSE80035)." (PMID 32972039, 2020). "In contrast, a potential cancer-promoting function of EFEMP1 was implied in two clinical studies; in one study, the level of EFEMP1 expression was correlated to poor prognosis for cervical cancer, while the other study demonstrated EFEMP1 over-expression in breast carcinoma." (PMID 21955618, 2011). "Fibulin-3, also known as EFEMP1, is known to inhibit angiogenesis and was found to be downregulated in sporadic breast carcinomas." (PMID 33371274, 2020). "Further, restoring EFEMP1 expression in breast cancer cells inhibited TGF-β signaling, breast cancer cell EMT, invasion and metastasis in vivo." (PMID 33182810, 2020).
breast carcinoma (continued). "The results showed that following EFEMP1 knockdown, the migration ability across the transwell membrane was significantly decreased in the upper compartment of the transwell units, suggesting that EFEMP1 is necessary for migration and might thus play a role in breast cancer metastasis." (PMID 27270657, 2016). "In data set GSE10797, we observed significant downregulation of EFEMP1 and upregulation of MMP1 in stromal cells of 28 breast cancer patients compared with stromal cells from 5 normal individuals who received reduction mammoplastic surgery." (PMID 27468688, 2016). "For example, overexpression of EFEMP1 eliminated tumor development and suppressed angiogenesis and VEGFA expression in hepatocellular carcinoma, gastric and prostate cancers, and glioblastoma, while the converse was true with ovarian and breast cancers." (PMID 34069906, 2021). "Indeed, stable transfection of Hs578T cells with an shRNA construct targeting EFEMP1 results in a significant suppression of cell migration across the transwell membrane, suggesting that EFEMP1 is necessary for migration and therefore might play roles in breast cancer metastasis." (PMID 27270657, 2016). "Taken together, these data suggest that HIF2α, but not HIF1α, mediates hypoxia-induced breast cancer growth and that EFEMP1 promotes BCSC renewal and tumor metastasis as a downstream effector of hypoxia-induced HIF2α during breast tumorigenesis." (PMID 27270657, 2016).
Doyne honeycomb retinal dystrophy (29 papers, 2009 to 2026). Doyne honeycomb retinal dystrophy (DHRD) is a condition that affects the eyes and causes vision loss. "EFEMP1 encodes a member of the fibulin family of extracellular matrix glycoproteins, and mutations in this gene have been shown to cause Doyne honeycomb retinal dystrophy and familial juvenile-onset open-angle glaucoma." (PMID 38984127, 2024). "EFEMP1 mutation is responsible for Doyne honeycomb retinal dystrophy, a maculopathy that has several common elements with AMD." (PMID 36362067, 2022). "DLL1 is required for normal eye development while EFEMP1 has been implicated in age-related macular degeneration and is also associated with Malattia Leventinese and Doyne honeycomb retinal dystrophy." (PMID 34638643, 2021). "EFEMP1 has been implicated in glaucoma in several genome-wide association studies (GWAS), macular degeneration, age-related macular dystrophy, and Doyne honeycomb retinal dystrophy." (PMID 32393163, 2020). "An R345W mutation in EFEMP1 causes Doyne honeycomb retinal dystrophy, which leads to activation of the alternative complement pathway in RPE cells." (PMID 32393163, 2020). "Doyne honeycomb retinal dystrophy (DHRD)/malattia leventinese (ML) is a rare allelic condition with massive drusen in the posterior fundus caused by EFEMP1 gene mutation." (PMID 30541486, 2018). "To highlight, EFEMP1 mutations are associated with Doyne honeycomb retinal dystrophy, an autosomal dominant disorder in which there are drusen (lipid) deposits in the macula eventually leading to vision loss." (PMID 29755398, 2018). "The R345W mutation of EFEMP1 is responsible for Doyne honeycomb retinal dystrophy (DHRD), a retinal degenerative disease clinically similar to AMD that afflicts patients decades earlier than AMD." (PMID 29730901, 2018). "A previous study suggests that a single mutation (p.Arg345Trp) in the last EGF domain of FBLN3/EFEMP1 gene causes Doyne honeycomb retinal dystrophy (DHRD; OMIM 126600)." (PMID 27007659, 2016). "EFEMP1 has also been associated with Doyne honeycomb retinal dystrophy and AMD." (PMID 39546296, 2024). "EFEMP1 mutation could lead to familial dominant drusen (Doyne Honeycomb Retinal Dystrophy), a genetic eye disease similar to AMD." (PMID 36911400, 2023). "In addition, two novel targets of HTRA1 have been identified: EFEMP1, an extracellular matrix protein mutated in Doyne honeycomb retinal dystrophy, a genetic eye disease similar to AMD, and thrombospondin 1 (TSP1), an inhibitor of angiogenesis." (PMID 29730901, 2018). "A point mutation in EFEMP1 causes an inherited early-onset form of macular degeneration called Malattia Leventinese/Doyne honeycomb retinal dystrophy (ML/DHRD)." (PMID 32911658, 2020). "A missense mutation in EFEMP1 (R345W) has been found in patients with Doyne honeycomb retinal dystrophy (DHRD)." (PMID 30102696, 2018). "Previous ocular genetic studies have identified a recurrent, missense mutation in exon-10 of EFEMP1 (c.1033C>T, p.R345W) associated with Doyne honeycomb retinal dystrophy (DHRD) and/or Malattia Leventinese (MLVT, MIM: 126600) in European and Asian families." (PMID 26162006, 2015). "R345W mutation in EFEMP-1 is linked to two inherited early–onset macular degenerative retinal diseases Malattia Leventinese (ML) and Doyne honeycomb retinal dystrophy (DHRD)." (PMID 24919117, 2014). "With respect to AMD, EFEMP-1 expressed in RPE cells is a high-risk gene associated with AMD and Doyne honeycomb retinal dystrophy." (PMID 24919117, 2014). "In one of these, Malattia leventinese or Doyne honeycomb retinal dystrophy (ML/DHRD), Fib3/EFEMP1 is mutated (R345W)." (PMID 23840815, 2013). "The region also contains 14 OMIM disease genes, two of which EFEMP1 (OMIM: 601,548) and BCL11A (OMIM: 606,557) are dominant and associated with the Doyne honeycomb degeneration of retina (OMIM: 126,600) and with the Dias − Logan syndrome (OMIM: 617,101), respectively." (PMID 36807877, 2023).
lung carcinoma (20 papers, 2013 to 2025). "In lung cancer cells, downregulated EFEMP1 is linked to tumor growth and invasion." (PMID 41367615, 2025). "On the contrary, EFEMP1 inhibited lung cancer cell invasion and metastasis and suppressed MMP-7 expression by activating Wnt/β-catenin signaling." (PMID 27351229, 2016). "For example, the levels of EFEMP1 mRNA and protein were found to be reduced in lung cancer tissues compared with normal tissues." (PMID 25987128, 2015). "EFEMP1 is associated with decreased MMP-2 and MMP-7 levels in lung cancer and MMP-2 and MMP-9 levels in endometrial carcinoma, which are also observed in highly metastasizing and rapidly expanding tumors." (PMID 25987128, 2015). "After transfection of control or EFEMP1 vector in lung cancer cells, the ability of colony formation and invasion was detected by colony formation experiment and matrigel invasion method." (PMID 25676403, 2015). "EFEMP1 negatively modulates the invasiveness of lung cancer cells by regulating p38-MAPK and MMP-2/9/7." (PMID 25987128, 2015). "The aim of this study is to investigate the functional effect and mechanism of EFEMP1 in lung cancer cell growth and invasion." (PMID 25676403, 2015). "Collectively, these results suggest that EFEMP1 functions as a suppressor of lung cancer growth and invasion." (PMID 25676403, 2015). "Epigenetic silencing of EFEMP1 promotes lung cancer invasion and metastasis by activating MMP-7 expression." (PMID 25676403, 2015). "In lung cancer stem cells, EFEMP1 could suppress invasion and migration of lung adenocarcinoma cells by modulating the IGF1R/PI3K/AKT/GSK3β pathway." (PMID 27351229, 2016). "Western blot result showed EFEMP1 expression was downregulated in lung cancer cells." (PMID 25676403, 2015). "Furthermore, EFEMP1 suppresses both the epithelial-to-mesenchymal transition and self-renewal of lung cancer stem cells by modulating the IGF1R/PI3K/AKT/GSK3β pathway." (PMID 25987128, 2015). "EFEMP1 expression in lung cancer cells was determined by Western blot." (PMID 25676403, 2015). "Luciferase assay was used to detect expression of MMP-7 reporter construct transfected with or without EFEMP1 in lung cancer cells." (PMID 25676403, 2015).
glioblastoma (19 papers, 2011 to 2025). The most malignant astrocytic tumor (WHO grade IV). "Using gene expression analysis of both TMZ-sensitive and TMZ-resistant glioblastoma cell lines, we demonstrated that overexpression of EFEMP1 is associated with a TMZ-resistant phenotype in glioblastoma cells." (PMID 24495907, 2014). "In addition, it is possible that BRCC3 effect could combine with other factors associated with TMZ resistance in glioblastoma, such as EFEMP1 (Fibulin-3), an extracellular matrix protein." (PMID 25337721, 2014). "EFEMP1, an angiogenesis promoter, poor prognostic marker in ovarian cancer, and potential therapeutic target in glioblastoma treatment, harbored a circRNA in HUVECs (22 circRNAs)." (PMID 28842720, 2017). "In our study, we show that EFEMP1 overexpression activates the Notch pathway in TMZ-resistant glioblastoma, while interference with the Notch pathway conveys partial sensitivity to TMZ-resistant glioblastoma cells." (PMID 24495907, 2014). "Moreover, by comparing the IC50 values of the WT, R1, and R2 glioblastoma cell lines to the corresponding EFEMP1 expression levels, we identified a positive correlation between these two variables (r2=0.56, p=0.021), suggesting that EFEMP1 expression is associated with a TMZ-resistant phenotype." (PMID 24495907, 2014). "EFEMP1 emerged as the most differentially expressed mRNA in all three glioblastoma cell lines with >2-fold (p<0.05) increased EFEMP1 expression in the TMZ-resistant glioblastoma subclones." (PMID 24495907, 2014). "Altogether these data suggest that GSIs can decrease Notch signaling in glioblastoma cells and potentiate the TMZ effect on glioblastoma cells that acquired EFEMP1-mediated TMZ-resistance." (PMID 24495907, 2014). "Silencing of EFEMP1 in glioblastoma cells resulted in decreased cell survival following TMZ treatment, whereas overexpression caused TMZ-resistance." (PMID 24495907, 2014). "Altogether our results suggest EFEMP1 as a potential therapeutic target to overcome TMZ-resistance in glioblastoma." (PMID 24495907, 2014). "In glioblastoma, EFEMP1 has been reported to stimulate tumor growth, invasion of tumor cells, and resistance to apoptosis." (PMID 24495907, 2014). "Previous report has indicated that miR-338-5p targets EFEMP1 in glioblastoma cells." (PMID 32056133, 2020). "Moreover, miR-338-5p suppressed the growth and metastasis of glioblastoma cells through directly targeting EFEMP1." (PMID 32056133, 2020). "EFEMP1 expression level correlates with survival in TMZ-treated glioblastoma patients." (PMID 25987128, 2015). "In order to determine whether EFEMP1 overexpression resulted in the activation of the Notch signaling pathway in the TMZ-resistant glioblastoma cells, we first assessed the expression of the Notch-induced genes HES1 and HEY1 by qRT-PCR." (PMID 24495907, 2014). "Moreover, EFEMP1 has been identified as an activator of Notch signaling which results in increased invasion, tumor cell self-renewal, chemoresistance, and glioblastoma growth." (PMID 24495907, 2014). "Here we identify by gene expression profiling of both TMZ-sensitive and non-canonical TMZ-resistant glioblastoma cell lines that expression of EFEMP1 is associated with a TMZ-resistant phenotype." (PMID 24495907, 2014). "In addition, we show that EFEMP1 expression levels correlate with survival in TMZ-treated glioblastoma patients." (PMID 24495907, 2014). "Therefore, it remains to be determined what the exact contribution of EFEMP1 to Notch signaling is in TMZ-resistant glioblastoma cells in relation to other factors that can induce Notch signaling, including MAGP-1/2, CCN3, YB-1, DLL, and Jagged." (PMID 24495907, 2014). "Here we demonstrate a significant role for EFEMP1 in TMZ-resistance of glioblastoma cells." (PMID 24495907, 2014). "Further research is needed to determine whether EFEMP1 level in glioblastoma tissue and/or in blood could serve as a stratification marker for the treatment of patients with TMZ and/or GSIs." (PMID 24495907, 2014).
glioblastoma (continued). "Inhibition of EFEMP1 and/or its downstream signaling components may be a potential therapeutic venue for the sensitization of glioblastoma cells to TMZ." (PMID 24495907, 2014). "In conclusion, we provide evidence for a role of EFEMP1 in TMZ-resistance in glioblastoma." (PMID 24495907, 2014). "Next we analyzed whether EFEMP1 expression is a predictive biomarker candidate for the efficacy of TMZ treatment in glioblastoma patients." (PMID 24495907, 2014). "In contrast, a potential cancer-suppressing function of EFEMP1 was found in the study of nasopharyngeal carcinomas, sporadic breast cancer, glioblastoma multiforme, and non-small cell lung cancer (NSCLC), Fibulin-3 was associated with tumour progression and inhibited cell migration and invasion." (PMID 24236050, 2013). "Real-time qRT-PCR was used to quantify EFEMP1 expression in 95 glioblastoma multiforme (GBM)." (PMID 21955618, 2011). "Although we had a limited number of samples, a clear trend could be observed towards an increased expression of EFEMP1 in glioblastoma samples at the time of progression, suggesting that EFEMP1 could be used as a marker for tumor progression after TMZ treatment." (PMID 24495907, 2014). "It would be of interest to determine whether EFEMP1 expression correlates with TMZ resistance and survival in this glioblastoma subclass." (PMID 24495907, 2014). "Subsequently, we determined whether blocking of the Notch pathway could overcome the EFEMP1-mediated resistance to TMZ, by treating the Hs683-WT and Hs683-Rl glioblastoma cells that demonstrated high expression of HES1/HEY1 with TMZ and the γ-secretase inhibitor (GSI) DAPT." (PMID 24495907, 2014). "To determine whether EFEMP1 can act as a sole effector of non-canonical TMZ-resistance in glioblastoma cells, we overexpressed EFEMP1 in Hs683 cells." (PMID 24495907, 2014). "Furthermore EFEMP1 can act on other pathways, including EGFR which could also convey resistance to glioblastoma cells and could explain that only partial sensitization to TMZ treatment is observed upon Notch inhibition." (PMID 24495907, 2014). "In addition, the discovery of the function of EFEMP1 as a tumor suppressor that modulates EGFR suggests a need to further investigate EFEMP1 as a potential predictive marker for anti-EGFR therapies of cancer, including glioblastoma, lung, breast, prostate, and liver cancers." (PMID 21955618, 2011). "Thus, EFEMP1 is a significant biomarker candidate for survival in the TMZ-treated group (p=0.044), but not in glioblastoma patients that are not treated with TMZ (p=0.46)." (PMID 24495907, 2014).
mesothelioma (19 papers, 2013 to 2025). A usually malignant and aggressive neoplasm of the mesothelium which is often associated with exposure to asbestos. "Finally, RNA sequencing of KPM cells comparative to normal pleural mesothelial cells revealed a distinctive transcriptomic signature that included classic mesothelioma markers (Msln, Spp1, Efemp1, Pdpn, Wt1) as well as new candidate mesothelioma genes." (PMID 34898002, 2022). "Recently, in pleural mesothelioma, it was noted that EFEMP1 could serve as a sensitive and specific biomarker to mesothelioma." (PMID 27015552, 2016). "In addition, plasma fibulin-3(EFEMP1) levels distinguish healthy persons who have been exposed to asbestos from patients with mesothelioma." (PMID 25987128, 2015). "Recently, in pleural mesothelioma, it was found that EFEMP1 was a sensitive and specific biomarker that could distinguish healthy individuals with exposure to asbestos from patients with mesothelioma." (PMID 23840707, 2013).